GFI1B (growth factor independent 1B transcriptional repressor)
Description:
Essential proto-oncogenic transcriptional regulator necessary for development and differentiation of erythroid and megakaryocytic lineages. Component of a RCOR-GFI-KDM1A-HDAC complex that suppresses, via histone deacetylase (HDAC) recruitment, a number of genes implicated in multilineage blood cell development and controls hematopoietic differentiation. Transcriptional repressor or activator depending on both promoter and cell type context; represses promoter activity of SOCS1 and SOCS3 and thus, may regulate cytokine signaling pathways. Cooperates with GATA1 to repress target gene transcription, such as the apoptosis regulator BCL2L1; GFI1B silencing in leukemic cell lines markedly increase apoptosis rate. Inhibits down-regulation of MYC and MYB as well as the cyclin-dependent kinase inhibitor CDKN1A/P21WAF1 in IL6-treated myelomonocytic cells. Represses expression of GATA3 in T-cell lymphomas and inhibits GATA1-mediated transcription; as GATA1 also mediates erythroid GFI1B transcription, both GATA1 and GFI1B participate in a feedback regulatory pathway controlling the expression of GFI1B gene in erythroid cells. Suppresses GATA1-mediated stimulation of GFI1B promoter through protein interaction. Binds to gamma-satellite DNA and to its own promoter, auto-repressing its own expression. Alters histone methylation by recruiting histone methyltransferase to target genes promoters. Plays a role in heterochromatin formation.
Synonyms: ZNF163B; BDPLT17
Tractability: Antibody: its Gene Ontology location is reachable by antibodies, with high confidence.
Gene: Protein-coding gene on chromosome 9 (132,944,000 to 132,991,687, forward strand). Ensembl gene ENSG00000165702.
Subcellular location: Nucleus
Subcellular location (Human Protein Atlas): Nucleoplasm; Plasma membrane
Gene Ontology:
Molecular function: protein binding; RNA polymerase II-specific DNA-binding transcription factor binding; sequence-specific double-stranded DNA binding; DNA-binding transcription activator activity, RNA polymerase II-specific; DNA-binding transcription factor activity, RNA polymerase II-specific; RNA polymerase II cis-regulatory region sequence-specific DNA binding
Biological process: negative regulation of transcription by RNA polymerase II; negative regulation of G1/S transition of mitotic cell cycle; regulation of hemopoiesis; regulation of transcription by RNA polymerase II; positive regulation of transcription by RNA polymerase II
Cellular component: nuclear matrix; nucleoplasm; nucleus; transcription regulator complex
Genetic constraint (gnomAD): Loss-of-function variants: 18 observed, 35.08 expected, observed/expected ratio (o/e) 0.51, 90% interval 0.35 to 0.76. The upper end of that interval is the gene's LOEUF score, 0.76, which puts it in group 3 of 6, group 1 being the genes least tolerant of losing a copy. Missense variants: 430 observed, 465.08 expected, observed/expected ratio (o/e) 0.92, 90% interval 0.85 to 1. Synonymous variants: 178 observed, 186.28 expected, observed/expected ratio (o/e) 0.96, 90% interval 0.85 to 1.08.
Gene-disease validity (ClinGen):
ClinGen rates the evidence that GFI1B causes each of these diseases.
platelet-type bleeding disorder 17 (autosomal dominant): Definitive.
Homologues: Orthologues: chimpanzee GFI1B (99% identical), macaque GFI1B (98% identical), pig GFI1B (93% identical), dog GFI1B (90% identical), rabbit GFI1B (87% identical), rat Gfi1b (86% identical), mouse Gfi1b (85% identical), guinea pig GFI1B (81% identical), tropical clawed frog gfi1b (63% identical), zebrafish gfi1b (61% identical). Paralogues in human: GFI1 (58% identical), BCL6B (22% identical), ZBTB49 (22% identical), BCL6 (22% identical), ZBTB14 (20% identical), ZBTB21 (19% identical), PRDM13 (19% identical), ZBTB7B (17% identical), FEZF2 (17% identical), FEZF1 (17% identical), ZBTB12 (16% identical), ZNF280B (16% identical), and 16 more.
Diseases named in the same sentence as GFI1B in open-access papers:
GFI1B is named in the same sentence as 41 diseases in open-access papers, as found by Europe PMC text mining. Sharing a sentence is not in itself a finding about the gene and the disease. The quoted sentences say what the papers report.
medulloblastoma (14 papers, 2015 to 2025). A malignant, invasive embryonal neoplasm arising from the cerebellum. "For medulloblastoma, we found SVs in noncoding regions that caused super-enhancer hijacking events of medulloblastoma driver genes (GFI1, GFI1B, and PRDM6)." (PMID 39322849, 2024). "In fact, local enhancer hijacking of GFI1 and distal enhancer hijacking of GFI1B drive medulloblastoma growth, either by cooperating with MYC to drive group 3 tumors or with other drivers to promote group 4 medulloblastoma development." (PMID 37568705, 2023). "In particular, GFI1/GFI1B overexpression was found to be a present in 15–20% of group 3 medulloblastoma and to play a significant role at the different stages of tumorigenesis." (PMID 37568705, 2023). "It has been shown previously that Growth Factor Independent Protein 1 (GFI1) and GFI1B are transactivated by enhancers in group 4 medulloblastoma and form a complex with LSD1 and CoREST that promotes tumour growth." (PMID 35379950, 2022). "For instance, the analysis of medulloblastoma genome sequencing data revealed that juxtapositioning of enhancers to neighboring genes leads to increased expression of oncogenes such as GFI1 or GFI1b in sub-groups of medulloblastoma cases." (PMID 31555592, 2019). "Other structural rearrangements place an enhancer near novel oncogenes, such as GFI1 and GFI1b in subtypes of medulloblastoma." (PMID 28333948, 2017). "Recently, the BARHL1/DDX31 super-enhancer was identified as an element that activates the GFI1B oncogene when fused to it by chromosomal deletion in subsets of Group 3 and Group 4 medulloblastomas." (PMID 27310018, 2016). "In addition, it was suggested that LSD1 inhibitors have promising anti-proliferative effects against GFI1/GFI1B-driven group 3/4 medulloblastomas." (PMID 37568705, 2023). "In fact, abnormal activation of GFI1B and GFI1 has been related to human medulloblastoma and is also likely to be relevant in blood malignancies." (PMID 28401061, 2017). "These include combination therapy with PI3K pathway inhibitors (BKM-120) and histone deacetylase inhibitors (LBH-589) for MYC-driven group 3 medulloblastoma, targeting LSD1 in MB with GFI1/GFI1B over-activation, CDK inhibitors, and cell cycle checkpoint inhibitors." (PMID 40229260, 2025). "In the G4 medulloblastomas, SVs affecting GFI1 and GFI1B and the recurrent tandem duplication of SNCAIP are known to cause overexpression of GFI1, GFI1B and PRDM6, respectively, by putting them under the control of super-enhancer regions (termed enhancer hijacking, EH)." (PMID 37576901, 2023). "Unlike blood malignancies, GFI1B and GFI1 activation has been associated with solid tumors, in particular medulloblastoma." (PMID 28401061, 2017). "The RNAseq results also indicate that GFI1 was not highly expressed and GFI1B transcripts were not present at all, indicating that GFI1 and GFI1B were not the MYC-cooperating genes in this medulloblastoma." (PMID 26380221, 2015). "While GFI1 and GFI1B overexpressing tumours show high LSD1 activity that could be blocked using specific chemical inhibitors, our findings show that inhibition of LSD1 increases stemness, raising caution over the use of LSD1 inhibitors in the treatment of specific subtypes of medulloblastoma." (PMID 35379950, 2022). "In addition to the BRCA2 6174delT, the medulloblastoma cells had amplification of MYC, deletion at Xp11.2, and isochromosome 17, but no structural variations or overexpression of GFI1 or GFI1B." (PMID 26380221, 2015).
leukemia (8 papers, 2011 to 2023). A malignant (clonal) hematologic disorder, involving hematopoietic stem cells and characterized by the presence of primitive or atypical myeloid or lymphoid cells in the bone marrow and the blood. "In the context of leukemia models deficiency of Gfi1b accelerates leukemia development both in a haploinsufficient, but also full knockout model." (PMID 36969082, 2023). "We found that venetoclax and FAO inhibitors exert better anti-leukemia effects by inhibiting mitochondrial respiration in GFI1B-deficient AML cells." (PMID 35804097, 2022). "The study showed that the number of leukemic stem cells (LCSs) was significantly increased upon loss of Gfi1b and was most likely responsible for driving leukemia development." (PMID 31508375, 2019). "Similarly, we reported GFI1B promoter mutations in human leukemias." (PMID 28401061, 2017). "Collectively, these data indicated that metabolic properties evolved during leukemia progression, and genetic alterations influenced metabolism reprogramming induced by GFI1B in AML cells." (PMID 35804097, 2022). "To explore the metabolic regulation of Gfi1b in leukemic cells and metabolic evolution during leukemogenesis, we determined metabolic phenotypes of Gfi1b-KO cells in different leukemia stages in murine AML models." (PMID 35804097, 2022). "We provided in vitro evidence that in MLL/AF9 leukemia FAO or OXPHOS inhibition significantly impeded the rapid progression of Gfi1b-KO cells." (PMID 35804097, 2022). "In a megakaryoblast leukemia cell line, it was shown that GFI1B induced growth inhibition strictly depended on the KDM1A interacting P2 and K8 in GFI1B's SNAG domain." (PMID 31649884, 2019). "Gfi1b repression of oncogene Meis1 also suggests that GFI1B is involved in leukemia when its repressor function is abolished." (PMID 28401061, 2017). "FAO or OXPHOS inhibition significantly impeded leukemia progression of Gfi1b-KO MLL/AF9 cells." (PMID 35804097, 2022). "Moreover, we observed that metabolic phenotypes evolved as cells progressed from preleukemia to leukemia, and the correlation between Gfi1b expression level and metabolic phenotype was affected by genetic variations in AML cells." (PMID 35804097, 2022). "This role of GFI1 and GFI1B bears high significance for the ongoing effort to generate hematopoietic stem and progenitor cells de novo for the autologous treatment of blood disorders such as leukemia and lymphoma." (PMID 33193732, 2020). "Collectively, the selective separation of LSD1 from GFI1B by NCD38 restores the ERG super-enhancer activation and consequently upregulates ERG expression, inducing the transdifferentiation linked to the anti-leukemia effect." (PMID 29765516, 2018). "In this review we will discuss the molecular function of the GFI1/GFI1B CoREST complex, and describe how targeting of this complex forces myeloblasts to differentiate at the molecular and cellular level and how this could improve treatment of leukemia." (PMID 31649884, 2019). "We observed a substantial decrease in colony numbers of rotenone-treated Gfi1b-WT and Gfi1b-KO MLL/AF9 cells, which supported our previous report about the high dependence on OXPHOS of MLL/AF9 leukemia." (PMID 35804097, 2022). "The progression from preleukemia to leukemia was accompanied by changes in the metabolic phenotype and interestingly, genetic variations in AML cells were found to have a great influence on the correlation between Gfi1b expression and the metabolic phenotype." (PMID 36969082, 2023).
lymphoma (5 papers, 2017 to 2025). A malignant (clonal) proliferation of B- lymphocytes or T- lymphocytes which involves the lymph nodes, bone marrow and/or extranodal sites. "The rs55799729-T allele was predicted to have stronger interaction with GFI1B, which functions as a transcriptional repressor and promotes growth arrest and apoptosis in lymphomas." (PMID 40646133, 2025). "Again, in this context, Gfi1b expression was decreased in the first lymphomas compared with the latest." (PMID 28401061, 2017). "Another piece of evidence of the implication of GFI1B reduction in lymphoma comes from its relation with B-cell lymphoma 6 (BCL6), a gene frequently expressed in T- and B-cell lymphomas." (PMID 28401061, 2017). "Gfi1b has been identified as a retrovirus integration site in diffuse large B-cell lymphomas of mice containing the human BCL6 transgene, but this was not the case in retroviral injected non-transgenic control lymphomas." (PMID 28401061, 2017).
acute myeloid leukemia (3 papers, 2017 to 2022). Acute myeloid leukemia (AML) is a group of neoplasms arising from precursor cells committed to the myeloid cell-line differentiation. "GFI1B is a transcriptional repressor that plays a critical role in hematopoiesis, and its expression is negatively related to the prognosis of acute myeloid leukemia (AML) patients." (PMID 35804097, 2022). "In keeping with this, GFI1B expression has been found in high levels in some primary CD34+ human acute myeloid leukemias (AMLs) and leukemic cell lines." (PMID 28401061, 2017). "Intriguingly, a somatic dominant-negative mutation D262N in the fourth zinc finger of GFI1B that decreases its function has been associated with malignant transformation in an acute myeloid leukemia patient." (PMID 33193732, 2020). "However, parts of this model have been challenged by new findings using acute myeloid leukemia cells lines that indicated that the enzymatic activity of LSD1 as a demethylase is not per se required to mediate the function of GFI1, and by inference also of GFI1B, as transcriptional repressors." (PMID 33193732, 2020).
erythroleukemia (3 papers, 2018 to 2023). Acute erythroid leukemia characterised by the presence of at least 50% erythroid precursors and at least 20% myeloblasts in the bone marrow. "The current findings suggest that the interaction between LSD1 and GFI1B is presumably an important PPI at least in erythroleukemia cells." (PMID 29765516, 2018). "These in silico findings suggest the possibility that LSD1 could suppress the ERG-SE by forming the complex with GFI1B in erythroleukemia cells." (PMID 29765516, 2018). "Erythroleukemia cell line, HEL92.1.7 was treated for different durations (3–48 h) with the dual inhibitor and differentiation markers GFI1b, CD11b and CD86 were assessed." (PMID 36595522, 2023).
Macrothrombocytopenia (3 papers, 2021 to 2026). "This raises the hypothesis that low GFI1B levels may cause macrothrombocytopenia at least partially via reducing TUBB1 expression." (PMID 38464330, 2025). "GFI1B-RT is characterized by the presence of truncated proteins lacking the zinc fingers of GFI1B, and mild to moderate bleeding disorder with macrothrombocytopenia." (PMID 34502524, 2021). "Interestingly, GFI1B loss also causes a macrothrombocytopenia phenotype in mice, and in our data, TUBB1 expression decreases quickly as a function of decreased GFI1B expression but then plateaus at a level that corresponds to loss of one copy of TUBB1." (PMID 41532405, 2026).
Thrombocytopenia (3 papers, 2020 to 2024). A reduction in the number of circulating thrombocytes. "Inherited pathogenic GFI1B variants result in thrombocytopenia and bleeding propensities with varying intensity." (PMID 38548886, 2024). "Likewise, it is possible to differentiate between GPS and GFI1B-related thrombocytopenia (GFI1B-RT), in the case of large and pale staining platelets in the May-Grünwald Giemsa (MGG) blood smear." (PMID 32079152, 2020).
anemia (2 papers, 2014 to 2022). A reduction in the number of red blood cells, the amount of hemoglobin, and/or the volume of packed red blood cells. "Probably as a result of the erythroid maturation defect, adult Gfi1b deficient mice suffer from anemia as indicated by the low RBC counts, the low hematocrit and hemoglobin levels." (PMID 24800817, 2014). "In addition, adult Gfi1b deficient mice also show extramedullary erythropoiesis, which may be a consequence of the anemia." (PMID 24800817, 2014). "Both the embryonic deletion of Gfi1b by EpoR-Cre and the deletion in adult mice by Mx-Cre or Cre-ERT leads to reduced numbers of erythroid precursors, perturbed and delayed erythroid maturation, anemia and extramedullary erythropoiesis." (PMID 24800817, 2014).
bleeding disorder (2 papers, 2017 to 2021). "Consistent with the Gfi1b KO effect on megakaryopoiesis, different mutations in GFI1B are involved in platelet-related bleeding disorders." (PMID 28401061, 2017). "Consistent with this, human mutations of GFI1B produce bleeding disorders with low platelet count and abnormal function." (PMID 28401061, 2017).
Intellectual disability (2 papers, 2025 to 2026). "FOXP1, a haploinsufficient and potentially triplosensitive transcription factor implicated in intellectual disability, exhibited a strong and dose-dependent response, particularly to varying levels of GFI1B." (PMID 38464330, 2025).
lung carcinoma (2 papers, 2021). "Among them, GFI1B, HLF, and ZNF750 acted as protective factors of lung cancer prognosis." (PMID 34925645, 2021).
myelodysplastic syndrome (2 papers, 2019 to 2022). A clonal hematopoietic disorder characterized by dysplasia and ineffective hematopoiesis in one or more of the hematopoietic cell lines. "Regarding GFI1B, a rare somatic missense variant in the DNA binding domain (D262N) was found in a patient upon transformation of myelodysplastic syndrome (MDS) to AML." (PMID 31649884, 2019). "Besides the regulation of normal hematopoiesis, low-level or loss of Gfi1b promotes AML development and negatively influences the prognosis of myelodysplastic syndrome (MDS)/AML patients." (PMID 35804097, 2022).
myeloid leukemia (2 papers, 2013 to 2017). A clonal proliferation of myeloid cells and their precursors in the bone marrow, peripheral blood, and spleen. "Over-expression of Gfi1 and Gfi1b have been observed in induced and naturally occurring lymphoid and myeloid leukemias in mice and humans respectively." (PMID 23308270, 2013). "Therefore, consistent with the importance of GFI1B block in myeloid leukemias, TCF3 inhibition in T-cell malignancies may work through GFI1B downregulation." (PMID 28401061, 2017).
neutropenia (2 papers, 2018 to 2023). A decrease in the number of neutrophils found in the blood. "In human and mice, GFI1B mutations are linked to severe neutropenia and platelet shape, number, and function." (PMID 37287538, 2023).
platelet disorder (2 papers, 2021). "GFI1B-related thrombocytopenia (GFI1B-RT) is a rare dominant congenital platelet disorder caused by mutations in the GFI1B gene." (PMID 34502524, 2021). "GFI1B mutations have been associated to a rare, dominant, congenital platelet disorder known as GFI1B-related thrombocytopenia (GFI1B-RT), caused by the presence of truncated GFI1B proteins with dominant-negative properties on megakaryocytopoiesis and thrombopoiesis." (PMID 34685575, 2021).
B-cell lymphomas (1 paper, 2017). "Additionally, GFI1B was decreased in human BCL6-positive T- and B-cell lymphomas, analyzed by immunohistochemistry." (PMID 28401061, 2017).
chronic myeloid leukemia (1 paper, 2017). "In chronic myeloid leukemia (CML), other myeloproliferative neoplasms (MPNs), AML, and B-lymphoblastic leukemias, GFI1B expression has also been observed to increase." (PMID 28401061, 2017).
diabetes mellitus (1 paper, 2023). A metabolic disorder characterized by abnormally high blood sugar levels due to diminished production of insulin or insulin resistance/desensitization. "Novel targets include MYO18A, SEC16A, CCNB1, MAD2L1, hsa-mir-4315, hsa-mir-6134, hsa-mir-9500, KIFC3, FBL (fibrillarin), TUBA1A and GFI1B might have crucial biologic functions in the pathogenesis of patients with diabetes mellitus and obesity." (PMID 36837510, 2023).
erythrocytosis (1 paper, 2021). "The Growth Factor Independent 1B Transcriptional Repressor (GFI1B) was confirmed as a novel candidate gene involved in the development of erythrocytosis in one of the previous studies." (PMID 34440324, 2021).
Hepatosplenomegaly (1 paper, 2024). Simultaneous enlargement of the liver and spleen. "Mouse Ezh2K20R/K20R mutants develop hepatosplenomegaly associated with high GFI1B expression, and Ezh2K20R/K20R mutant bone marrows expand hematopoietic stem cells and downstream hematopoietic populations." (PMID 38346162, 2024).